IL6 (interleukin 6)
Diseases named in the same sentence as IL6 in open-access papers (continued):
Sharing a sentence is not in itself a finding about the gene and the disease.
cancer (continued). "The information above all emphasized the positive relationship between IL-6 expression and cancer development." (PMID 34568032, 2021). "IL-6 regulates various cancer hallmarks and multiple signaling pathways, such as JAK/STAT3, Ras/MAPK, and PI3K– PKB/Akt." (PMID 34178680, 2021). "Inflammatory cytokines released by adipocyte, such as TNF-α, IL-6, are also able to affect cancer lipid metabolism with paracrine and endocrine activity, which will be discussed later." (PMID 34888248, 2021). "In this study, we aim to reveal the role of HMGA2 in TNBC biology and demonstrate a link between HMGA2-mediated cancer phenotypes and the regulation of NF-kB/IL-6/STAT3 signaling." (PMID 34680349, 2021). "ESCC cells can secrete IL-6 and other pro-inflammatory cytokines, including IL-8 and LIF, which have been implicated in cancer progression and immune evasion through the activation of STAT3 and YAP." (PMID 34063828, 2021). "In rodent cancer models, aerobic ET has also been shown to decrease plasma IL-6 concentrations and the cytokine content of adipose tissue." (PMID 33801684, 2021). "Considering the inter-triggering mechanism of cancer progression and inflammation, we assessed the production of pro-inflammatory cytokines, including IL-6, TNF-α, and IFN-γ, and the anti-inflammatory cytokine IL-10 in CAC mice in colon tissue and serum." (PMID 33996624, 2021). "Among these cytokines, only recombinant IL-6 was able to significantly induce LRG1 expression in cancer cells." (PMID 34930899, 2021). "The IL-6/JAK/STAT3 signaling pathway is aberrantly hyperactivated in patients with hematopoietic malignancies or solid tumors in cancer patients." (PMID 34638439, 2021). "High levels of circulating IL-6 in the blood correlate with metastasis and poor prognosis in several types of cancers." (PMID 34223877, 2021). "Another potent key immune-modulating SASP, IL-6, recruits myeloid-derived suppressor cells to cancer tissue." (PMID 34916607, 2021). "In our pan-cancer analysis, we found a strong and significant correlation between inflammatory (IL6, CXCL8, IL12, TGFβ) and suppressive cytokines (IL10) with EMT score." (PMID 35096592, 2021). "Interleukin-6 (IL-6) is a multifunctional cytokine that participates in the progression of many kinds of malignant tumours." (PMID 35004308, 2021). "IL-6 is relevant to the early diagnosis of many diseases such as diabetes and Alzheimer’s as well as being a biomarker over-expressed by several types of cancer, including head and neck squamous cell carcinoma, breast, oral, cervical and colorectal cancer." (PMID 34443939, 2021). "Many signaling pathways, including IL-6/STAT3 (interleukin-6/signal transducer and activator of transcription 3), play crucial roles in cancer initiation and progression." (PMID 34901003, 2021). "Strikingly, IL-6 was localized in Rab37-associated vesicles in THP-1 cells, which was further enhanced by cancer-CM." (PMID 34093869, 2021). "In conclusion, we demonstrate here that STING is an important contributor to the rapid IL-6 production frequently seen upon DNA damage in cancer cells." (PMID 35087822, 2021). "We propose that transformed cancer cells produce inflammatory cytokines such as IL-6, which act in a paracrine fashion on resident lung macrophages to produce SAA." (PMID 34203378, 2021). "Collectively, these analyses revealed that while IL-6 was rapidly induced in 50% of cancer cells by DNA damage, this induction was often independent of that of ISGs." (PMID 35087822, 2021). "On the other hand, adipocytes interact with cancer cells mainly through adipokine secretion, such as IL-6 or Leptin, or through the modulation of cancer cell metabolism." (PMID 34359819, 2021). "To evaluate the role of IL-6-induced BECN1 Y333 phosphorylation in cancer therapy, we first used a CRC model and assessed the potential role of IL-6 in CRC chemotherapy resistance." (PMID 34131122, 2021).
cancer (continued). "The next objective was to determine the potential role of IL-6, a proinflammatory cytokine, on the Rictor signaling pathway in prostate epithelial and cancer cells." (PMID 34682865, 2021). "In particular, we investigate how TZB-induced CSCs with modified IL-6 landscapes shape the cognitive functions in cancer patients." (PMID 34669701, 2021). "IL-6 enhances cancer cell migration and EMT by activating STAT3 and IL-11 to facilitate resistance to chemotherapeutic drugs." (PMID 34063828, 2021). "The elevated levels of various cytokines, including TNF-α, IL8 and IL6, have been found in the serum of cancer patients treated with gemcitabine." (PMID 34771621, 2021). "Activation of IL-6/STAT3 signaling induces HCC cancer stemness and promotes HCC cancer stem cell expansion." (PMID 33669204, 2021). "One of the cytokines most frequently examined in both mouse and human studies with respect to the early stages of cancer formation is IL-6." (PMID 34638361, 2021). "IL-6 stimulates Bcl-2 and Bcl-XL synthesis in cancer cells, resulting in the prevention of apoptosis after cytotoxic therapy." (PMID 33472580, 2021). "The IL‐6/JAK1 pathway was reported to drive PD‐L1 Y112 phosphorylation to promote cancer immune evasion." (PMID 33523587, 2021). "In the early phases of cancer cachexia, the inhibition of IL-6 can revert the browning of the WAT in a mouse model." (PMID 34440886, 2021). "Alterations have been detected in the levels of cytokines (e.g., adiponectin and ~11-fold increase in IL-6), as well as their tissue expression (e.g., five-fold increase in IL-6 in the subcutaneous AT (sAT)) in cachectic vs. weight-stable cancer patients." (PMID 33557173, 2021). "IL-6 is also a significant element in other physiological disfunctions such as activity of cancer cells." (PMID 34900966, 2021). "Interleukin-6 (IL-6) is a multipotent cytokine that plays an important role in immune responses and human diseases, including different type of cancers." (PMID 33806019, 2021). "Noteworthy, the production of IL-6 and IL-8 synergistically activates the expression of NF-kB effectors, which subsequently maintain cell growth and survival, inflammatory events, and cancer development." (PMID 34513674, 2021). "The inflammatory cytokines IFN-γ, IL-6 and IL-10 were also found at significantly higher levels in the cancer secretome compared to the normal secretome." (PMID 33540635, 2021). "In details, IL-6 is produced in a variety of cells such as fibroblasts, endothelial cells, keratinocytes, macrophages, T cells and mast cells but also by cancer tissue and cancer cell lines." (PMID 34944975, 2021). "Trabectedin and lurbinectedin also reduce the production of growth factors, angiogenic and pro-inflammatory mediators such as CCL2, IL-6, CXCL8, MIF, and IL-6 in cancer cells, monocytes, and TAMs." (PMID 33026575, 2021). "This is the case of IL-6, which has been shown to have a direct effect on cancer cell growth and survival, as well as on resistance to therapy." (PMID 34948097, 2021). "It has been proved that the IL6/JAK/STAT3/SIGNALING pathway was aberrantly hyperactivated in various types of cancer that had a strong relationship with poor clinical prognosis." (PMID 34712264, 2021). "In breast cancer, CSCs are regulated by MSCs via cytokines like CXCL-7 and IL-6, thus promoting cancer progression." (PMID 33472580, 2021). "Colocalization of IL-6 with Rab37-containing vesicles was increased in close proximity of plasma membrane (PM) in the cancer-CM treated THP-1 monocytes (Regions 3 and 4)." (PMID 34093869, 2021). "Activation of inflammatory or innate immune signaling in cancer, such as IL-6/JAK/STAT3 axis, NF-κB, and interferon signaling, can promote tumor cell survival." (PMID 34071428, 2021). "The anti-cancer effects of sesamin have been attributed to its ability to reduce significantly the expression of NF-KΒ, IL6 and transcriptional target of STAT3." (PMID 33578642, 2021).
cancer (continued). "In an in vivo model, IL-6 secretion from MDSC endows cancer cell stem-cell-like properties by activating the IL-6/STAT3 signaling pathway." (PMID 34689842, 2021). "It has been shown that cytokines, especially IL-6, IL-18 and TNFα, are involved in both inflammaging and different chronic conditions such as heart disease, kidney disease and cancer." (PMID 34444668, 2021). "What is more, multiple studies have shown that IL‐6 or its downstream signalling is capable of expanding CSCs in cancers of the breast, colon, ovary, lung, brain, and head and neck." (PMID 34075691, 2021). "Along with IL-6, it forms a tandem helpful in the diagnostics of cancer, including ovarian malignancies—serous epithelial ovarian cancer." (PMID 34572929, 2021). "In coordination with immune function, IL-15 facilitates the expansion and maintenance of NK-cells and effector T-cells, while IL-6 has been shown to promote trafficking and tumor infiltration of exercise-mobilized NK-cells in several murine cancer models." (PMID 33555464, 2021). "We found that patients bearing a CCA with low stromal IL-6 and active autophagy flux in the cancer cells have the best prognosis and this correlates with a more effective response to post-operative chemotherapy." (PMID 33925189, 2021). "Here, we focus on the role of HMGA2 in the biology of TNBC and demonstrate a link between HMGA2-mediated cancer phenotypes and regulation of NF-kB/IL-6/STAT3 signaling." (PMID 34680349, 2021). "IL-6 can regulate the crosstalk between CSCs and cancer cells through constitutive activation of Stat3, and plays an important role in the formation of mammospheres." (PMID 33804152, 2021). "The resulting M2 macrophages can in turn promote cancer progression by releasing inflammatory mediators (including IL-6, tumor necrosis factor, interferon-γ, proteases, ROS, and nitrogen compounds)." (PMID 34074799, 2021). "IL-6 through STAT mediated induction of cancer cell stemness is also controlled by epigenetic processes." (PMID 34722553, 2021). "The IL6-JAK-STAT3 pathway is always aberrantly hyperactivated in many cancer types, and this phenomenon is often associated with poor outcomes." (PMID 34660570, 2021). "The most significant association of inflammatory parameters with cancer risk were detected for CRP (39.8%), fibrinogen (24%), IL6 (25%) and TNFα (24%)." (PMID 34685542, 2021). "It has been reported that several cytokines, including GM-CSF, IL-6, IL-8, and macrophage migration inhibitory factor (MIF), are highly expressed by the cancer-associated MSCs." (PMID 34073849, 2021). "The effects of both cytokines IL-6 and IL-17 have a major impact on several chronic diseases, such as chronic viral infection and cancer development." (PMID 33750983, 2021). "In vivo studies assessing CYP activity in cancer patients have assessed concentrations of the pro-inflammatory mediators IL-1β, IL-6, IL-8, TNF-α, TGF, and the acute phase response protein, CRP15,20,25." (PMID 33707475, 2021). "The NF-κB signaling pathway, a critically vital signaling pathway in tumorigenesis, regulates numerous downstream cancer-promoting genes, including some proangiogenesis cytokines, such as IL-6, IL-8, and VEGF." (PMID 33791378, 2021). "Interleukin 6 (IL-6), a pro-inflammatory cytokine, mediates pro-survival signals in cancer and inflammations." (PMID 34834397, 2021). "IL-6 is another key cytokine, secreted by cancer cells, immune cells and CAFs, which inhibits apoptosis of cancer cells through STAT3 activation." (PMID 34503172, 2021). "In this study, we investigate how IL-6 regulates cancer chemotherapy resistance in an autophagy-dependent manner." (PMID 34131122, 2021). "As for cancer, the IL-6-signaling pathway represents an attractive target for therapeutic or preventive interventions even for infectious diseases and chronic inflammatory diseases." (PMID 34884178, 2021).
cancer (continued). "IL-6 is the major driver of cancer cachexia and activates the JAK/STAT signaling that is associated with muscle wasting in cancer cachexia." (PMID 33801569, 2021). "IL-6 is mainly secreted by a variety of immune cells and is also highly expressed in a variety of cancer cells." (PMID 34863141, 2021). "Our analyses of a dataset of 42 STING-expressing cancer cell lines demonstrated the frequent induction of IL-6 upon topoisomerase 1 and 2 inhibition in ≥ 50% of the cells, often independent of a marked ISG response." (PMID 35087822, 2021). "Our previous studies have identified that TME-derived IL-6 is acutely induced following chemotherapy treatment, activating cancer cell anti-apoptotic signaling and shielding lymphoma cells from cell death." (PMID 34711820, 2021). "The JAK/STAT signaling pathway is the main pathway of IL-6, which is constitutively activated by IL-6 and frequently observed in a variety of human cancers, including NPC." (PMID 34165442, 2021). "It has been shown that IL-6 trans-signaling is involved in many pathophysiologic states including autoimmunity and cancer." (PMID 34141712, 2021). "NF-κB links inflammation to cancer via factors such as cyclins, Bcl-2 family members, IL-6, and cyclooxygenase-2." (PMID 33578830, 2021). "Interleukin-6 (IL-6) is a proinflammatory cytokine driving systemic inflammation that leads to cancer cachexia." (PMID 33801569, 2021). "In the context of exercise and cancer immunology, interleukin (IL)‐15 and IL‐6 have been studied extensively and modulate the innate and adaptive immune system." (PMID 32478975, 2021). "STAT3, highly active in more than 50% of BCs, has been described as a key signalling orchestrator of many of the cancer-promoting effects exerted by IL6, but also IL11, LIF and OSM." (PMID 34834425, 2021). "A growing number of studies have corroborated the role of the proinflammatory IL-6 in influencing the main aspects of cancer biology." (PMID 34576335, 2021). "For instance, tumors affect their surroundings by secreting extracellular signaling molecules such as tumor growth factor-β (TGF-β), carbonic anhydrase IX (CA IX), and interleukin-6 (IL-6) that stimulate cancer progression." (PMID 34957091, 2021). "In this study, cancer patients with higher concentration of TNF-α, IL-2R, IL-6, IL-8, and IL-10 had higher risk of death." (PMID 33735106, 2021). "For example, Abraxane treatment can drive CXCL10 expression by PDAC cells, resulting in diminished CAF secretion of IL-6 and reduced cancer cell migration and invasion." (PMID 34638468, 2021). "CAFs produce several cytokines such as IL-6, IL-11, and IL-22 and create a favorable environment for cancer." (PMID 34063828, 2021). "In addition, IL-6 produced by CAFs not only has an immunosuppressive effect, but increases cholesterol uptake, which may be linked to the upregulated steroid biosynthesis and cholesterol metabolism by cancer cells." (PMID 33805737, 2021). "Interleukin-6 (IL-6), which plays a significant role in cancer progression, is a pleiotropic factor that belongs to a cytokine subfamily." (PMID 34960256, 2021). "Pre-clinical evidence has suggested the promise of olamkicept as an agent with potential to inhibit the role of IL6 in inflammation and cancer." (PMID 34834425, 2021). "Our main objective was to analyze the usefulness of four different biomarkers (CRP, PCT, IL-6 and MR-proADM) as outcome predictors in febrile pediatric patients with cancer." (PMID 34828740, 2021). "Regarding the epigenetic modulation of IL6 pathway, the IL-6 expression is affected by DNA methylation of promoter region in several cancers." (PMID 34576335, 2021). "Cytokines secreted by TAMs induce anti-apoptotic programs in cancer cells, such as IL-6 derived from TAMs that mediate the resistance of solid tumors to many chemotherapies via activating TGF-β pathway." (PMID 34040139, 2021).
cancer (continued). "CAF-secreted IL-6 enhances migration and invasion of cancer cells, inducing the expression of EMT and metastatic-related genes." (PMID 34572947, 2021). "IL‐6 acts directly on cancer cells to trigger the expression of STAT3 target genes, the encoded proteins of which then drive cancer cell proliferation and survival, promoting angiogenesis, invasiveness, metastasis, and immunosuppression." (PMID 34131122, 2021). "TGF-β induces the release of IL-6 via the NF-κB signaling pathway, whereas IL-6 promotes cancer stemness through STAT3 activation." (PMID 34202411, 2021). "Multifunctional pro-inflammatory cytokine IL-6 was found in multiple cancer cell lines and tissues of cancer patients what suggests that this protein is involved in the pathogenesis of various cancers." (PMID 34681200, 2021). "IL-6 can be an activator to induce the phosphorylation of STAT3, so in order to further explore the antitumor mechanism, we treated cancer cells with IL-6 after the combination therapy." (PMID 34900688, 2021). "IL-6 also sustains cancer cell lysis through the activation of C-reactive protein (CRP) and its binding to the phospholipids of cancer cells, which, in turn, activates the component 1q of the complement system." (PMID 33923292, 2021). "The phenomenon of feedback regulation of IL-6 in cancer cells has received more attention than that in NPCs for many reasons." (PMID 34321087, 2021). "It has been found that a chamomile extract obtained by steam distillation can reduce DNA synthesis in human cancer cells and inhibit leukotrienes and IL-6 (interleukin 6) production." (PMID 35009033, 2021). "The aberrant IL-6 expression contributes to the profound consequences in metastasis, resistance, and stemness properties of cancer cells." (PMID 34551797, 2021). "The bone marrow microenvironment contains several growth factors along with IL-6 released by the bone matrix and osteoblasts, creating an ideal situation for the promotion of oncogenesis in various cancers including MM." (PMID 34771643, 2021). "The IL-6 overexpression is has reported in various cancers, especially from epithelial histogenesis and hematological malignancies." (PMID 34178680, 2021). "The prospect of targeting IL-6 in cancer settings still needs to be explored by more future studies." (PMID 33429846, 2021). "Intriguing, the expression of IL-6 was seen in many malignant tumors like breast cancer, lung cancer, GBM and prostate cancer." (PMID 34199460, 2021). "Cancer cachexia is largely characterized by systemic inflammation, including increased proinflammatory cytokines such as interleukin 1 (IL-1), interleukin 6 (IL-6), or tumor necrosis factor α (TNFα)." (PMID 34945009, 2021). "Similar analysis including IL-1β, Rantes/CCL5, MCP1, GMCSF, TNFα, and IL-6 showed similar results with elevated IL-6 increasing the probability of having a cancer diagnosis (p < 0.0046)." (PMID 35048057, 2021). "To date, although studies have demonstrated IL-6's role in mediating the progression of tumors, its contribution to the pathogenesis of chronic inflammatory diseases and cancer remains incompletely understood." (PMID 33552492, 2021). "Cancer cell-intrinsic functions of IL6 include promoting proliferation and survival thereby functioning as a bypass pathway in the setting of EGFR-specific TKIs31." (PMID 34001994, 2021). "Various TLR ligands are also reported to increase the proliferation of cancer cells via cytokines such as IL-6 and subsequent signaling." (PMID 34804118, 2021). "IL6/STAT3 pathway had been demonstrated that played a contributing factor for multidrug resistance in cancer." (PMID 34373835, 2021). "Fisher’s exact test indicated a significant inverse correlation of IL-6 positive staining in cancer cells and fibrotic areas and the drug regimen status (p < 0.025)." (PMID 33925189, 2021). "Cancer-associated inflammation is mediated by infiltration of leukocytes and secretion of various cytokines such as TNF-α, IL-6, IL-8, TGF-β1, and IL-10." (PMID 34778599, 2021).